RAB25 (RAB25, member RAS oncogene family)
Diseases named in the same sentence as RAB25 in open-access papers (continued):
Sharing a sentence is not in itself a finding about the gene and the disease.
breast carcinoma (continued). "In contrast, recent studies showed that Rab25 expression is decreased in human colon cancers and triple-negative (negative for estrogen receptor (ER), progesterone receptor (PR), and Her2/Neu) breast cancers, and Rab25 functions as a tumor suppressor in these cancers." (PMID 22121362, 2012). "The investigators also suggested that Rab25 was overexpressed in breast cancers." (PMID 21063400, 2011). "However, other studies have shown that RAB25 is a tumor suppressor that prevents cell migration and proliferation in head and neck squamous carcinoma, colorectal cancer and claudin-low breast cancer." (PMID 30445998, 2018). "Thus a Rab25 may target cargo to different subcellular compartments in different breast cancer subsets thus contributing to the differential function in these subsets." (PMID 27259233, 2016). "However, up- and downregulation of RAB25 has been documented in breast cancer." (PMID 25351113, 2015). "Hence, resistance to TRAIL across breast cancer cell lines could potentially be due to Rab25-induced OPG secretion as seen in our HEY and MCF7 models." (PMID 25520884, 2013). "Ten genes, including CCNB1, CDH1, KDR, RAB25, PRKCA, etc., found which can maintain the high accordance of mRNA–protein for both breast cancer patients and cell lines in basal-like subtypes for the first time." (PMID 36360219, 2022). "We also found that our deep-learning classifier predicted well (AUC > 0.65) on the CNA status in breast cancer, including six genes of FGFR1, EIF4EBP1, KAT6A, HEY1, ZNF217, and RAB25." (PMID 34556802, 2021). "In ZEB2-induced EMT, RAB25 down-regulation facilitates migration of cell lines from different origins, such as luminal-like (MCF7) or claudin-low (MDA-MB-231) breast cancer cells, and skin squamous carcinoma (A431) or colorectal cancer cells (HT29)." (PMID 30445998, 2018). "Knocking-down ZEB2 (ZEB2-KD) in the mesenchymal-like MDA-MB-231 breast cancer cell line (which expresses more endogenous ZEB2 and less RAB25 than MCF7 cells) induced the expression of RAB25 and CDH1." (PMID 30445998, 2018). "Suppression of both in vitro cell growth and in vivo xenograft development were observed after knockdown of Rab25 in glioblastoma multiforme cells (U87MG) and breast cancer cells (MCF7)." (PMID 28969096, 2017). "Thus while Rab25 is a key player in the EMT phenotype in claudin low breast cancer the exact mechanism remains unknown with the potential that the function of proteins mediating apicobasal polarity as well as other transcriptional pathways remains to be explored." (PMID 27259233, 2016). "In cell lines and primary breast cancer tissue, ZEB1 reduces the expression of Both RAB25 and ESRP1, which have tumor suppressor functions." (PMID 26646320, 2016). "Rab25 and its effector, Rab Coupling Protein (RCP) are frequently coamplified and coordinately elevated in ER+ve breast cancers." (PMID 27259233, 2016). "Continuing our efforts to understand the dichotomy of Rab25 expression and function in the context of cell lineage we utilized an existing well-documented Lysophosphatidic Acid Receptor (LPA) driven mammary tumor model." (PMID 27259233, 2016). "Therefore, Rab25 could be used as a biological marker for breast cancer." (PMID 25815277, 2015). "To assess the generalizability of the role of Rab25 in regulating OPG and protecting cells from the effects of TRAIL, we utilized MCF7 breast cancer cells as a model, as they express both Rab25 and OPG." (PMID 25520884, 2013). "Thus, Rab25 could be used as a biological marker of breast cancer." (PMID 21143914, 2010). "Indeed, ectopic expression of Rab25 induces apoptosis and suppresses the angiogenic properties of the triple-negative MDA-MB-231 breast cancer cell line." (PMID 32842549, 2020). "Interestingly, most breast cancer subtypes expressed a high level of ZEB2 and low level of RAB25, except in claudin-low subtype in which RAB25 has been described as a tumor suppressor." (PMID 30445998, 2018).
breast carcinoma (continued). "Knockdown of Rab25 reduced phospho-ERK1/2 level and promoted cell proliferation in breast cancer." (PMID 28969096, 2017). "We found that exogenous expression of Rab25 in the HMLE Snail cells, at levels comparable to those constitutively expressed in luminal breast cancer cells, could robustly oppose Snail-driven invasion through MatrigelTM (p = 0.016)." (PMID 27259233, 2016). "Gain of 1q in cancer, specifically in breast cancer has previously been described but is impressively evidenced in this study by frequent co-amplification of the SYK-regulated SPRR1A, SPRR1B, MUC1, RAB25, and ADAM15, genes located within chromosome 1q." (PMID 24523870, 2014). "Expression of Rab25 to levels similar to those in tumors with RAB25 amplification, increased OPG mRNA expression and secretion from ovarian and breast cancer cell lines, whereas down regulation with Rab25 specific siRNA decreased OPG secretion and sensitized cells to TRAIL-induced cell death." (PMID 25520884, 2013). "Studies have also demonstrated that knockdown of vimentin resulted in downregulation of genes involved in breast cancer invasion and the basal-like phenotype, including Axl, ITGB4, and PLAU, with a subsequent upregulation in the genes abundant in normal mammary epithelium, including RAB25 and EHF." (PMID 34769002, 2021). "Further, brain metastases derived from multiple breast cancer cell lines showed more than 15 fold increase of Rab11b expression compared with cultured cells, with no change in Rab11a or Rab25 levels, suggesting the brain metastatic microenvironment specifically influences Rab11b expression." (PMID 32541798, 2020). "Additionally, we found that absence of Rab25 is a clinically reliable tool to detect claudin-low breast cancers." (PMID 27259233, 2016). "Rab25 and RCP may act as biomarkers to further stratify breast cancer patients further." (PMID 27259233, 2016).
colon cancer (17 papers, 2011 to 2024). "Rab25 expression is associated with colon cancer progression, and was thus investigated in the present study." (PMID 29515334, 2018). "Besides, loss of Rab25 prominent reductions in integrin β1 and promotes integrin β1 away from the lateral membranes in colon cancer." (PMID 34141705, 2021). "The result was further supported by another Rab25 deficiency study in colon cancer." (PMID 28969096, 2017). "Loss of Rab25 in human colon cancers was associated with poorer patient prognosis." (PMID 28969096, 2017). "Loss of Rab25 in human colon cancers is associated with poorer patient prognosis." (PMID 21063400, 2011). "Notably, the loss of Rab25 in human colon cancers has been linked to poorer patient prognosis." (PMID 37693315, 2023). "Rab25 is another Rab that functions as a tumor suppressor in colon cancer as increasing malignant tumor formation in intestinal epithelial cells from the ApcMin/−; Rab25−/− mice are observed." (PMID 35927755, 2022). "Nevertheless, further studies on the respective effects of EGF, integrin β1, and Rab25 in the progression and metastasis of colon cancer would enable the therapeutic application of these drugs." (PMID 29515334, 2018). "For this, we transfected HCT116 colon cancer cells with Rab25-specific siRNA and confirmed sufficient knockdown by western blotting." (PMID 29515334, 2018). "Integrin β1 is recycled by trafficking and shed from colon cancer cells in response to EGF stimulation in a Rab25-dependent manner." (PMID 29515334, 2018). "Integrin β1 is shed from colon cancer cells in response to EGF stimulation in a Rab25-dependent manner." (PMID 29515334, 2018). "Tumor suppressor function of Rab25 has also been found in several types of cancer, including colon cancer, head and neck cancer, esophageal squamous cell carcinoma and oral and oropharyngeal squamous cell carcinoma." (PMID 28969096, 2017). "Rab25 can be a tumor suppressor in colon cancer, but promotes tumor growth in several different cancer types." (PMID 26054340, 2015). "We therefore were surprised to find that >80% of Smad3+/−; Rab25−/− mice demonstrated large invasive colon tumours throughout the colon by 15 weeks of age." (PMID 21063400, 2011). "However, Rab25 was decreased in colon cancer and lower Rab25 expression levels correlated with poor patient prognosis." (PMID 33718142, 2021). "However, low expression of Rab25 is correlated with a poor prognosis in colon cancer, suggesting its role in tumor inhibition." (PMID 34141705, 2021). "Integrin β1 localization is regulated by the guanosine-5′-triphosphate hydrolase Rab25 and integrin β1 levels are elevated in the serum of colon cancer patients; thus, the present study examined the effects of epidermal growth factor (EGF) and Rab25 on integrin β1 localization in colon cancer cells." (PMID 29515334, 2018). "Similar to findings reported in ESCC and colon cancer, our results indicate that RAB25 could be a tumor suppressor gene in HNSCCs." (PMID 24403269, 2013). "We have investigated the role of Rab25 in colon cancer patients." (PMID 21063400, 2011). "Similarly, in colon cancers, changes in Rab25 expression may lead to alterations in Ras through changes in competition between Rab25 and Ras for Rab11-FIP1C." (PMID 21063400, 2011). "Although Rab25-deficient mice do not develop spontaneous colon tumours, breeding of ApcMin mice onto the Rab25-deficient background induces a marked increase in tumours, and crossing of Smad3+/− mice onto the Rab25 knockout background yields large invasive tumours." (PMID 21063400, 2011). "In two independent patient cohorts, gene microarray studies demonstrated that Rab25 expression was decreased in colon cancers independent of clinical and pathological staging." (PMID 21063400, 2011).
colon cancer (continued). "Interestingly, a recent study reported that overexpression of CLDN7 in colon cancer induced epithelial features and suppressed EMT through upregulation of Rab25 then decreased expression of p-Src and mitogen-activated protein kinase–extracellular signal–regulated kinase 1/2." (PMID 30428910, 2018).
non-small cell lung carcinoma (8 papers, 2010 to 2024). A group of at least three distinct histological types of lung cancer, including non-small cell squamous cell carcinoma, adenocarcinoma, and large cell carcinoma. "In conclusion, our study reveals overexpress MALAT-1 cause the drug resistance of EGFR-TKIs in non-small cell lung cancer (NSCLC) through the MALAT-1/miR-125/Rab25 axis." (PMID 39196297, 2024). "Additionally, RAB25 may be linked to tumor aggressiveness and metastasis, and S100P may be a diagnostic marker of non-small-cell lung cancer." (PMID 20142997, 2010). "Knockdown of Rab25 suppressed in vitro cell migration and cell invasion in renal cell carcinoma cells, advanced non-small cell lung cancer cells, prostate cancer cells and glioblastoma multiforme cells." (PMID 28969096, 2017). "And in non-small-cell lung cancer, Rab25-medicated integrin β1 activates AKT/β-catenin pathway." (PMID 34141705, 2021). "Aberrant expression of RAB25 promotes tumorigenesis of skin squamous cell carcinoma, while HLF down-regulation promotes distant metastases in non-small cell lung cancer." (PMID 34221975, 2021). "In non-small-cell lung cancer cells, ZEB2 expression was weak regardless of the RAB25 expression level." (PMID 30445998, 2018).
bladder cancer (6 papers, 2015 to 2024). "Moreover, high level of Rab25 expression was associated with lymph node/distant metastasis in bladder cancer, prostate cancer, gastric cancer and hepatocellular carcinoma, suggesting the involvement of Rab25 in promoting tumor metastasis." (PMID 28969096, 2017). "In addition, overexpression of GGT-II enzyme substrates such as Rab25, Rab5 and Rab7, has been reported in breast, ovarian, prostate and bladder cancers, and for some of these substrate mutation is a determinant of the aggressiveness of the cancer and a predictor of poor outcome." (PMID 28808351, 2017). "As such, overexpression of Rab25 contributed to bladder cancer metastasis through the induction of EMT." (PMID 34906074, 2021). "In the study of bladder cancer, Rab25 knockdown not only suppress in vitro cell migration but also reduce in vivo tumor metastasis." (PMID 28969096, 2017). "Rab25 knockdown reduced phospho-Akt level, leading to the reduction of cell migration/invasion in bladder cancer cell, hepatocellular carcinoma cells and glioblastoma multiforme cells." (PMID 28969096, 2017). "Tail vein injection of Rab25 knockdown bladder cancer cells (EJ, T24) into immune-compromised mice has resulted in less tumor nodule formation in lung compared with the mice injected with parental bladder cancer cells." (PMID 28969096, 2017). "Overexpression of Rab25 contributes to metastasis of bladder cancer through the induction of EMT." (PMID 25823663, 2015). "However, we demonstrated that CLIC3, mainly located in the nucleus, could interact with NAT10, but not with Rab25, to promote cell proliferation in bladder cancer." (PMID 38182571, 2024).
colorectal cancer (6 papers, 2012 to 2022). A primary or metastatic malignant neoplasm that affects the colon or rectum. "Conversely, in colorectal cancer, RAB25 expression is decreased, and this loss has been associated with poorer survival." (PMID 34771571, 2021). "Rab25 has tumor suppressor function in several types of cancer, including colorectal cancer, esophageal squamous cell carcinoma and head and neck squamous cell carcinoma." (PMID 28969096, 2017). "Rab25 knockdown Caco2-BBE colorectal cancer cells demonstrated twofold increase in the number of soft agar colonies formation and a significant increase in colony size than the control cell line." (PMID 28969096, 2017). "However, the tumor suppressor function of Rab25 was reported in several cancers, such as colorectal cancer, indicating the tumor type-specific function of Rab25." (PMID 35154286, 2022). "Another known direct target of GRHL2 is RAB25, a tumor-suppressor gene in colorectal cancer." (PMID 34771571, 2021). "However, tumor suppressor function of Rab25 was reported in several cancers, such as colorectal cancer, indicating the tumor type-specific function of Rab25." (PMID 28969096, 2017). "In the study of colorectal cancer, Rab25 acts as a tumor suppressor gene." (PMID 28969096, 2017). "Rab expression profiles are modulated under different disease conditions, such as Rab25 expression is altered in breast and colorectal carcinomas, and induce the invasive ability of cancer cells by interfering with the endosomal trafficking of cell adhesion proteins such as β-intergrins." (PMID 25261375, 2014).
esophageal squamous cell carcinoma (6 papers, 2013 to 2024). Esophageal squamous cell carcinoma (ESCC) is a type of esophageal carcinoma (EC) that can affect any part of the esophagus, but is usually located in the upper or middle third. "Ectopic overexpression of Rab25 in esophageal squamous cell carcinoma inhibited in vivo xenograft tumor development and angiogenesis." (PMID 28969096, 2017). "Lower expression of Rab25 correlated with significantly shorter survival time of patients with colorectal adenocarcinomas and esophageal squamous cell carcinoma (ESCC)." (PMID 28969096, 2017). "Rab25 enhances the aggressiveness in ovarian and breast cancer cells, while it functions as a tumor suppressor in esophageal squamous cell carcinoma and colorectal carcinoma." (PMID 27716280, 2016). "Furthermore, the reduced expression of RAB25 was shown to correlate with the decreased overall survival and was documented in esophageal squamous cell carcinoma (EScc) cell lines compared to pooled normal tissues." (PMID 37693315, 2023). "Epigenetic regulation also led to down-regulation of Rab25 in oral and oropharyngeal squamous cell carcinoma (OOSCC) and esophageal squamous cell carcinoma (ESCC), in which Rab25 acts as a tumor suppressor." (PMID 28969096, 2017).
triple-negative breast carcinoma (6 papers, 2013 to 2024). An invasive breast carcinoma which is negative for expression of estrogen receptor (ER), progesterone receptor (PR), and human epidermal growth factor receptor 2 (HER2). "Likewise, antibody-drug conjugates that can target these tumors and deliver a synthetically lethal payload to exploit the loss of the rab25 pathway may be an effective therapeutic strategy to target this subset of ras mutant triple-negative breast cancers." (PMID 38803515, 2024). "We next sought to confirm our findings using BT20 triple-negative breast cancer cells, which express Rab4a, Rab4b, Rab11a, Rab11b and Rab25." (PMID 37232246, 2023). "It has recently been suggested that RAB25 may act as a tumor suppressor in colon, esophageal, and triple-negative breast cancers." (PMID 24403269, 2013). "Loss of RAB25 was associated with human colorectal adenocarcinomas and triple-negative breast cancer, but the gene has not yet been investigated in relationship to tyrosine kinase resistance." (PMID 23555683, 2013). "For example, Rab25 has been reported to act as an oncogene in breast, ovarian, lung, GBM and gastric cancer and as a tumour suppressor in colon, oesophageal, head and neck and triple-negative breast cancer." (PMID 38638676, 2024).
head and neck squamous cell carcinoma (5 papers, 2013 to 2021). A squamous cell carcinoma that arises from any of the following anatomic sites: lip and oral cavity, nasal cavity, paranasal sinuses, pharynx, larynx, and salivary glands. "In the study of head and neck squamous cell carcinoma, Rab25 ectopic overexpression reduced in vitro cell invasion and in vivo tumor metastasis to cervical lymph node." (PMID 28969096, 2017).
colorectal adenocarcinoma (4 papers, 2013 to 2017). The most common type of colorectal carcinoma. "When Rab25 acts as a tumor suppressor, Rab25-deficiency reduced β1 integrin recycling to the plasma membrane and decreased tumor formation in colorectal adenocarcinomas." (PMID 28969096, 2017). "Moreover, they showed that human colorectal adenocarcinomas exhibited a reduction in RAB25 expression independently of tumor stage." (PMID 24403269, 2013).
gastric cancer (4 papers, 2017 to 2024). A primary or metastatic malignant neoplasm involving the stomach. "Suppression of cell invasion after Rab25 knockdown was observed in gastric cancer cells." (PMID 28969096, 2017).
lung adenocarcinoma (4 papers, 2019 to 2025). A carcinoma that arises from the lung and is characterized by the presence of malignant glandular epithelial cells. "In our previous research, we confirmed that miR-125 induces resistance to EGFR-TKIs in lung adenocarcinoma by upregulating its target gene Rab25 through the PI3K/AKT signaling pathway." (PMID 39196297, 2024). "It influenced the expression of downstream gene Rab25 and increased drug resistance in lung adenocarcinoma cells." (PMID 39196297, 2024). "Interestingly, Rab25 downregulation was found to impair EGFR signalling, with a consequent reduction in ERK and AKT phosphorylation in radioresistant lung adenocarcinoma and nasopharyngeal carcinoma cells." (PMID 40164572, 2025).